RNU5B-6P (RNA, U5B small nuclear 6, pseudogene)
Gene: Small nuclear RNA gene on chromosome 10 (109,184,934 to 109,185,001, reverse strand). Ensembl gene ENSG00000252574.
Homologues: Orthologues: chimpanzee U5 (100% identical), dog U5 (91% identical), mouse Gm23102 (90% identical), rabbit U5 (82% identical). Paralogues in human: RNU5E-10P (90% identical), RNU5B-2P (88% identical), RNU5A-5P (87% identical), RNU5E-3P (87% identical), RNU5E-7P (87% identical), RNU5E-4P (85% identical), RNU5F-4P (85% identical), RNU5F-6P (85% identical), RNU5F-7P (85% identical), RNU5A-4P (84% identical), RNU5A-8P (82% identical), RNU5E-8P (82% identical), and 13 more.